SUV39H1 (SUV39H1 histone lysine methyltransferase)
Diseases named in the same sentence as SUV39H1 in open-access papers (continued):
Sharing a sentence is not in itself a finding about the gene and the disease.
cancer (continued). "To evaluate the role of SUV39H1 and G9a in cancers, first we established clones of PC3, in which either of these 2 HMTs were stably downregulated by shRNA." (PMID 18446223, 2008). "Mutation analysis of HDAC1, HDAC2, SUV39H1, and SUV39H2 revealed only two out of 181 cancer samples (both cell lines) with significant coding-sequence alterations." (PMID 16638127, 2006). "We also screened HDAC1, HDAC2, SUV39H1, and SUV39H2 for mutations in 65 cancer cell lines and 116 primary tumours." (PMID 16638127, 2006). "SUV39H1 plays a crucial role in the development and progression of various cancers." (PMID 40059829, 2025). "In this study, we investigated the functional importance of SUV39H1 in cancer stem cells in GBM." (PMID 40059829, 2025). "In addition, SUV39H1 and SUV39H2 are also markers for the development of different cancers, with high or low expression of SUV39H1 posing risks, while high expression of SUV39H2 is often detrimental in most cases." (PMID 40750792, 2025). "The transcriptional level of SUV39H1 is elevated in various cancer tissues." (PMID 38650654, 2024). "The GEPIA database was used to analyze the expression of SUV39H1 in various cancer tissues." (PMID 38650654, 2024). "Furthermore, the multifaceted roles of SUV39H1 in cancer cells and T cells, such as regulating tumorigenesis, progression, T cell memory formation, and exhaustion, have enlightened us to explore more possibilities." (PMID 38645666, 2024). "A growing number of reports strongly suggest that SUV39H1 may be an interesting target for anti-cancer therapy." (PMID 39519018, 2024). "Thus, deleting SUV39H1 in cancer cells slowed down the tumor growth through cGAS demethylation‐mediated enhanced antitumor immunity in solid tumors." (PMID 38645666, 2024). "It has been reported that the role of SUV39H1 in cancer is a double-edged sword." (PMID 38017386, 2023). "The function of SUV39H1 in cancer development is pleiotropic." (PMID 35069908, 2022). "Suv39H1 knockdown represses cell proliferation; thus, Suv39H1 might be a promising target for cancer therapy." (PMID 35619625, 2022). "We then asked whether the signature of Suv39h1-KO CD8+ T cells that increase after anti-PD-1 in the mice is relevant to human cancer." (PMID 35768432, 2022). "Therefore, FBXO44/SUV39H1 inhibition can enhance cancer cell immunogenicity and overcome ICB resistance via the transcriptional regulation of IFNγ signaling." (PMID 34385592, 2022). "Moreover, our data showed that reduced miR-744 in cancer cell-derived EVs contributes to upregulation of SUV39H1." (PMID 33472665, 2021). "SUV39H1 attenuates the apoptosis of cancer cells and enhances the immune escape of tumor cells." (PMID 33985534, 2021). "FBXO44/SUV39H1 inhibitors could hold promise as stand-alone cancer therapies or enhancers of onco-immunotherapy response." (PMID 33681705, 2021). "Given that FBXO44/SUV39H1 inhibition enhanced cancer cell immunogenicity, we next examined if it could modulate antitumor immune response using a preclinical mouse breast cancer model." (PMID 33681705, 2021). "Our previous observation indicates that SUV39H1 may mediate the anti-cancer effects of metformin by inhibiting PCa cell migration, and SUV39H1 could serve as a therapeutic target for PCa treatment." (PMID 33066102, 2020). "Previous studies reported that chaetocin could reduce suv39h1, suv39h2, and G9a mRNA or their protein in ovine cells and human cancer cells." (PMID 32650566, 2020). "Furthermore, in the dysregulation in cancer, SUV39H1 is reported to play a tumor-suppressor role due to its cell proliferation-suppressing activity." (PMID 30348215, 2018). "According to our expression profile analysis, SUV39H1 is also overexpressed in some cancers." (PMID 25487737, 2014). "It has been suggested that the SUV39H1-mediated H3K9me3 mark on heterochromatin is a widespread mark of the senescence program and that this program could be targeted for cancer therapies." (PMID 23705022, 2013).
cancer (continued). "Our data suggested that SUV39H1 KD in cancer cells have shorter telomeres." (PMID 18446223, 2008). "Another indication suggesting SUV39H1 might be important in cancer, comes from the study revealing the interaction of SUV39H1 with Rb and also that Rb mutants found in human cancers fail to bind SUV39H1." (PMID 16638127, 2006). "However, whether SUV39H1 also regulates stemness maintenance in cancer stem cells of other cancer types remains to be determined in future studies." (PMID 40059829, 2025). "Although higher expression at the mRNA level is likely independent of Ub-mediated degradation, poorer disease-free survival with increased SUV39H1 may indicate a generally adverse effect of high SUV39H1 in cancer progression, highlighting the importance of regulating SUV39H1 abundance and activity." (PMID 41125851, 2025). "Thus, we speculated that reduced expression of miR-744 in cancer cell-derived EVs enhanced SUV39H1, which further suppressed the expression of Smad9 and consequently elevated the BMP4 expression, promoting the NSCLC progression." (PMID 33472665, 2021). "The mechanisms underlying the down-regulation of SUV39H1 may not be a cell-specific effect, because similar down-regulation of mRNA levels of SUV39H1 also was observed in other cancer cells such as HCC827, H460, LNCaP, and MCF-7 (data not shown)." (PMID 34066975, 2021). "Kaplan–Meier analysis of survival across a dataset of 33 types of cancer (GEPIA2) showed that higher expression of SUV39H1 correlates with poorer disease-free survival (Fig. EV7E)." (PMID 41125851, 2025). "We show here a putative disparity in survival outcomes for cancer patients when stratified by expression of both TRIP12 and SUV39H1." (PMID 41125851, 2025). "Suppressor of variegation 3–9 homolog 1 (Suv39H1), a SET domain-containing histone methyltransferase, has been reported to participate in tumorigenesis in various types of cancer." (PMID 38424632, 2024). "SUV39H1 and EZH2 has emerged as a drug target and results from studies conducted on SUV39H1 and EZH2 have helped in the development of several potential therapeutic strategies that can be followed to treat cancer." (PMID 36028818, 2022). "Overall, our findings unveiled a mechanism whereby miR-744 delivered by NSCLC-derived EVs upregulated SUV39H1, activating the Smad9/BMP9 axis and thus promoted cancer development." (PMID 33472665, 2021). "Euchromatic histone lysine methyltransferase 2 (G9a, EHMT2) and suppressor of variegation 3-9 homolog 1 (SUV39H1) predominantly methylate histone H3K9 to induce the formation of heterochromatin, and are overexpressed in several types of cancer." (PMID 30544763, 2018). "Among them, SETDB1, SUV39H1 and EZH2 are reported to be frequently over-expressed in various cancers, such as GCs, those of which functions are shown as oncogenic activities." (PMID 27572307, 2016). "On the other hand, enzymes that deposit repressive histone marks, such as the H3K9 trimethylases SETDB1 or SUV39H1/2, and the H3K27 trimethylase EZH2 are overexpressed in most cancer types studied." (PMID 25484917, 2014). "Importantly, we found that the histone H3K9 methyltransferase, SUV39H1, was released from the ER-promoter since presence of SUV39H1 has been shown to be crucial for maintenance of the H3-methylation and epigenetic control of heterochromatin assembly in cancer cells." (PMID 22662208, 2012). "In summary, our study reported that FBXO44 recruits SUV39H1, CRL4RBBP4/7, and Mi-2/NuRD to form a repressive epigenetic complex at the replication fork that promotes H3K9me3-mediated RE silencing post-DNA replication in cancer cells." (PMID 33681705, 2021). "Inhibition of FBXO44 or its co-factor SUV39H1 stimulated antiviral pathways and interferon (IFN) signaling and induced replication stress and DNA double-strand breaks (DSBs) in cancer cells, leading to restricted tumor growth and synergy with anti-PD-1 therapy." (PMID 33681705, 2021).
cancer (continued). "Moreover, SUV39H1-mediated H3K9 trimethylation regulates the expression of several genes, and the dysregulation of SUV39H1 is observed in different cancers." (PMID 34357075, 2021). "Whereas the roles of the histone methyltransferases SUV39H1 and SUV39H2 have been investigated in the context of cancer in humans and mice, the role of SUV39H2 in epidermal differentiation in mice, humans and dogs is virtually unknown." (PMID 32119674, 2020). "Overexpression of SUV39h1 and SUV39H2 has been reported in various cancers." (PMID 26695186, 2015). "Since SUV39h1-mediated H3K9 tri-methylation has been consistently linked to gene silencing, the observed transcriptional activation of cancer-related genes is likely an indirect consequence of the induction of SUV39h1 activity by HBx rather than the result of its recruitment to those target genes." (PMID 33923385, 2021). "Moreover, the repressive effect of Suv39h1 on cell cycle suppressor, including p15 and p16, plays more important role than proinflammatory phenotypes in VSMC pathological activation, which is consistent with previous studies in cancer." (PMID 31736204, 2020). "Besides LSD1, enzymes involved in histone lysine methyltransferases and lysine demethylases, such as SUV39H1 (KMT1A), SETDB1 (KMT1E), KDM4B, and KDM5A, have been found to be involved in the DDR, suggesting that their inhibitors have combination therapy potential with PARPi for cancer treatment." (PMID 37973845, 2023).
tumor (68 papers, 2006 to 2025). "Immune phenotype and single cell RNAseq analysis show that Suv39h1-deficient CD8+ tumor-infiltrating lymphocytes (TIL) display phenotypic characteristics of exhausted cells, including high expression of multiple inhibitory checkpoints." (PMID 35768432, 2022). "We conclude that Suv39h1 deficiency in the host not only delays tumor growth to levels similar to anti-PD-1 administration, but also synergizes with anti-PD-1 treatment." (PMID 35768432, 2022). "Since Suv39h1 genetic deficiency or pharmacological inhibition both re-activate anti-tumor immune responses, and promote re-programing by anti-PD-1, the role of Suv39h1 in this process must be at least partially non-redundant." (PMID 35768432, 2022). "To further understand the implication of Suv39h1-deficient CD8+ T cells in tumor-rejection, we investigated how Suv39h1-defective T cells behave in a Graft vs. Host Disease/Graft vs. Leukemia (GvHD/GVL) model." (PMID 35768432, 2022). "Methylation of lysine 9 on histone H3 by the methyltransferase G9a and SUV39H1 is associated with inhibition of tumor suppressor genes." (PMID 25978433, 2015). "To determine if the histone methyltransferase (HMT) activity of SUV39H1 played a role in tumor suppression, we utilized SUV39H1 constructs with point mutations in the enzymatic SET domain that have been shown to lack methyltransferase activity." (PMID 23705022, 2013). "Therefore, in this adoptive T cell transfer model Suv39h1-deficient T cells develop into much more potent effectors (that reject the tumor and attack the host) than their Suv39h1-proficient counterparts." (PMID 35768432, 2022). "Indeed, while mice injected with WT T cells died from tumor development, the ones injected with Suv39h1-deficient T cells died from GvHD (78%)." (PMID 35768432, 2022). "To investigate the specific role of Suv39h1-deficient T cells in the observed tumor rejection phenotype, we adoptively transferred in vitro activated control WT and Suv39h1-KO OVA-specific T cell receptor (TCR) transgenic OT-1 cells to B6 mice bearing established EL4-OVA tumors." (PMID 35768432, 2022). "Both SUV39H1/2 knock-out mice and SUV39H1 transgenic mice showed severe developmental defects, while the knockout animals exhibited decreased viability, increased genomic instability, and susceptibility to tumor formation." (PMID 29018479, 2017). "We should keep in mind that mice deficient in SUV39H1 HMTs (which target lysine 9 of histone H3) have increased chromosomal instability and tumour risk and another K9-H3 histone methyltransferase, RIZ1, undergoes CpG island hypermethylation-associated silencing in many tumour types." (PMID 16404435, 2006). "The impact of targeting SUV39H1 on the in vivo tumor formation ability of GSCs was assessed using a xenograft mouse model." (PMID 40059829, 2025). "Understanding the roles of SUV39H1 in various cell types within the tumor microenvironment is crucial for evaluating the therapeutic potential of SUV39H1 inhibitors for GBM treatment." (PMID 40059829, 2025). "Suv39H1 is widely considered as a tumor suppressor due to its activities in inhibiting proliferation-related genes and promoting senescence." (PMID 38424632, 2024). "As such, inhibiting SUV39H1 by F5446 in mouse breast cancer model augmented the sensitivity to anti-PD-1 treatment, reduced tumor progression, and increased survival." (PMID 39519018, 2024). "Chaetocin is a specific inhibitor of SUV39H1 both in vitro and in vivo and plays an effective anti-tumor role in various malignancies." (PMID 38976080, 2024). "We used Chaetocin treatment ectopic xenograft tumor derived from CAL27 cells to further determine SUV39H1 function in OSCC." (PMID 38650654, 2024).
tumor (continued). "Chaetocin is a non-specific inhibitor of SUV39H1, which can only partially explain the effects of inhibiting SUV39H1 on tumor growth and intracellular molecular expression." (PMID 38650654, 2024). "In vivo experiment chaetocin treatment significantly inhibit the growth of tumor, and reduce SUV39H1, Notch1, CD31 expression." (PMID 38650654, 2024). "For in vivo experiments, the use of Chaetocin cannot fully represent the effect of SUV39H1 knockdown on tumor biological behavior, which needs to be further verified by gene editing technology." (PMID 38650654, 2024). "This is consistent with solid tumors in which decitabine impairs SUV39H1 recruitment and inhibits H3K9me3, thereby blocking tumor cell growth and metastasis." (PMID 37798292, 2023). "We show here that genetic ablation or pharmacological inhibition of histone lysine methyltransferase Suv39h1 delays tumor growth and potentiates tumor rejection by anti-PD-1." (PMID 35768432, 2022). "The expressions of HOTAIR and Suv39H1 in BC cell lines and 20 pairs of BC and matched tumor-adjacent normal tissues were measured using qRT-PCR to verify the clinical significance of LncRNA HOTAIR and Suv39H1 in BC." (PMID 35619625, 2022). "We conclude that pharmacological inhibition of Suv39h1 augments the efficacy of anti-PD-1 blockade in this tumor model." (PMID 35768432, 2022). "By analogy to other non-redundant immunosuppressive proteins whose inhibition unleashes anti-tumor immune responses (often referred to as “immune checkpoints”), Suv39h1 can be considered as an “epigenetic immune checkpoint”." (PMID 35768432, 2022). "In colon cancer, SUV39H1 negatively regulates Fas transcription and impairs the sensitivity of tumor cells to CTL Fas L-mediated cytotoxicity." (PMID 36713412, 2022). "In Suv39h1-KO littermates, the growth of the tumor is similarly delayed, with a small number of tumor rejections (2/25), while treatment with anti-PD-1 induces complete tumor rejection in almost one-third of the mice (5/16)." (PMID 35768432, 2022). "Using both genetic and pharmacological approaches, we show that Suv39h1 inhibition overcomes tumor resistance to anti-PD-1 treatment." (PMID 35768432, 2022). "Overall, Suv39h1 inhibition enhances anti-tumor immune responses, alone or combined with anti-PD-1, suggesting that Suv39h1 is an “epigenetic checkpoint” for tumor immunity." (PMID 35768432, 2022). "Generally, SUV39H1 is regarded as a tumor suppressor for its role in inhibition of genes required for cell proliferation." (PMID 35069908, 2022). "Western blot analysis indicated that Suv39H1 levels significantly decreased in tumor tissues of the HOTAIR silencing group (p < 0.05)." (PMID 35619625, 2022). "Should the role of Suv39h1 be conserved in human T cells, its blockade would open new perspectives for the epigenetic manipulation of anti-tumor T cell responses in the clinic." (PMID 35768432, 2022). "While mice injected with WT T cells showed a high tumor incidence (more than 60% had detectable tumor cells) and developed mild GvHD, the mice injected with Suv39h1-KO T cells showed instead a lower tumor incidence (20%) and developed more severe GvHD." (PMID 35768432, 2022). "Targeting FBXO44 by genetic knockdown or pharmacologic inhibition of SUV39H1 restrained the proliferation of breast, lung, colon, and glioblastoma cancer cells in vitro and tumor growth in immunodeficient mice." (PMID 33681705, 2021). "Several lines of evidence documented a tumor suppressive role of SUV39H1 through its stabilization and silencing of heterochromatin." (PMID 34357075, 2021). "We also investigated SUV39H1 expression levels in A549 xenografts and found that upon treatment with H1299-EVs or H522-EVs, the expression of SUV39H1 was enhanced in tumor tissues of mice as compared to that upon treatment with BEAS-2B-EVs." (PMID 33472665, 2021).